MC4R (melanocortin 4 receptor)
Diseases named in the same sentence as MC4R in open-access papers (continued):
Sharing a sentence is not in itself a finding about the gene and the disease.
Obesity (continued). "In addition, MC4R is linked to other aberrant feeding behaviors and obesity-related comorbidities, including binge eating disorder, cardiovascular disease, and hypertension." (PMID 35571924, 2022). "A few MC4R genetic variants have been associated with FM, weight, and obesity risk." (PMID 36555722, 2022). "Genetic variations, including nonsynonymous mutations in MC4R, are a leading cause of obesity." (PMID 35807283, 2022). "Finally, evidence has been found that Attention-Deficit/Hyperactivity Disorder (ADHD) is related to obesity, since the mutation of the gene that encodes the MC4R protein (C271R) that causes obesity is also associated with ADHD." (PMID 35276953, 2022). "Furthermore, we found that the protective alleles against obesity (MC4R rs17782313 T and PPARG rs1801282 C) were associated with weight loss effectiveness." (PMID 35292917, 2022). "The loss of constitutive activity in MC4R mutations is considered as one cause of obesity." (PMID 35204745, 2022). "Loss-of-function variants in melanocortin 4 receptor (MC4R) are associated with obesity in humans." (PMID 35381001, 2022). "Loss-of-function mutations in MC4R are the most frequent genetic cause of obesity in humans." (PMID 35757435, 2022). "Mutations in the MC4R gene were reported as the most common cause of monogenic obesity." (PMID 35495128, 2022). "Loss of cilia in MC4R-expressing neurons causes obesity, hyperphagia, and increased body lengths." (PMID 36568981, 2022). "Furthermore, variants in MC3R and MC4R have been shown to be closely associated with monogenic human obesity." (PMID 35204745, 2022). "In a systematic review of the Lausanne Cohort 65+, rs10128072 was associated with fat mass and waist circumference, whereas the rs34114122 variant found in the MC4R gene was associated with obesity, high fat mass, and high food intake in the Hispanic population." (PMID 35741707, 2022). "Indeed, rs17782313 and rs12970134 in MC4R gene polymorphisms were associated with obesity in both European and Asian adults and children." (PMID 36452324, 2022). "They showed that in vitro confirmed loss of function rare variants in the melanocortin 4 receptor gene (a gene known to cause monogenic obesity) have a substantial effect on body weight, whereas studies lacking functional characterization mostly find much smaller effects." (PMID 36292633, 2022). "In humans, MC4R mutations constitute the most common known monogenic cause of obesity." (PMID 36555433, 2022). "To determine whether the response to bariatric surgery differs according to the presence of the MC4R Ile269Asn mutation, we genotyped 206 female patients with obesity previously submitted to RYGB." (PMID 36553534, 2022). "According to a recent systematic review, the polymorphisms rs9939609 FTO and rs17782313 MC4R could be associated with overweight and obesity in children and adolescents." (PMID 36499740, 2022). "The defect in basal activities of MC4R mutations can cause obesity." (PMID 36358958, 2022). "More recently, in vivo studies in humanized mouse models bearing the R165W human MC4R mutant showed that UM013086 rescued PM expression and function of this obesity-causing mutant MC4R in mice; treated animals restored the anorexigenic response to the MC4R agonist melanotan II." (PMID 36093106, 2022). "After correcting for multiple testing (P< 0.05/1703), a significant local genetic correlation was only observed for adult BMI and PCOS at chr18: 57630483–59020751, a genetic region harboring MC4R, a locus previously reported to be associated with adult BMI, childhood BMI and obesity in PCOS." (PMID 35144605, 2022). "MC4R widely expressed in the central nervous system (CNS), and its mutations could lead to monogenic obesity in human." (PMID 35250878, 2022). "Furthermore, a null Mc4r allele in mice leads to severe obesity due to hyperphagia and decreased energy expenditure." (PMID 35782067, 2022).
Obesity (continued). "MC4R-deficient mice are another very useful strain for use in human obesity research." (PMID 35782067, 2022). "Inactivated MC4R gene is associated with lower blood pressure (BP), independently of obesity." (PMID 36050672, 2022). "MC4R mutations in humans may induce obesity via haploinsufficiency, dominant-negative action, or a combination of the two resulting receptor functional changes." (PMID 35268815, 2022). "Recent studies have reported that the minor allele (C allele) for melanocortin 4 receptor (MC4R) rs17782313 may be related to the incidence of obesity and the risk of CVD." (PMID 36050672, 2022). "Moreover, obesity is negatively correlated with MSNA in persons heterozygous for functional melanocortin-4 receptor mutations." (PMID 36711125, 2022). "In MC4R-KO mice, the increased energy expenditure may be a primary cause of the anti-obesity effect; therefore, it exceeded the effect of the inhabitation of lipid absorption." (PMID 35710868, 2022). "Melanocortin-4 receptor mutations prevalently cause monogenetic obesity." (PMID 36362948, 2022). "Mean Native American ancestry of the chromosome 18 segment containing the MC4R Ile269Asn mutation was estimated in 206 patients with obesity, and was 58% in wildtype homozygous individuals, 79% in heterozygous patients and 100% in the Asn269Asn homozygous patient." (PMID 36553534, 2022). "FTO rs9930506 and MC4R rs17782313 polymorphisms and obesity in children." (PMID 36499740, 2022). "Moreover, MC4R agonists lead to weight loss in people with obesity due to genetic disruption of the melanocortin pathway." (PMID 36175420, 2022). "This connection between these neurons and MC4R might affect the higher prevalence of general obesity in older women with MC4R gene variants." (PMID 36233190, 2022). "Our findings suggest that while the presence of a single MC4R loss of function Ile269Asn allele significantly increases obesity risk, the presence of at least one functional MC4R allele seems sufficient to allow short-term weight loss in response to dietary restriction, phentermine and RYGB." (PMID 36553534, 2022). "More than 170 variants of MC4R have been reported to be linked to hyperphagia and early-onset obesity and, in contrast, several variants alleviate the pathology by lowering BMI and other obesity-associated conditions, referred to as gain of function (GoF) mutations." (PMID 35807283, 2022). "The rs6232 polymorphism of the gene that codes for PCSK1 has also been associated with both childhood and adult obesity; likewise, the rs2229616 polymorphism of the MC4R gene has been associated with an increased risk of developing type 2 diabetes mellitus in Saudi patients." (PMID 35741707, 2022). "The most prevalent genetic cause of obesity is a mutation in the Melanocortin 4 receptor (MC4R) gene, which encodes the melanocortin 4 receptor and is expressed in the hypothalamus, and obesity, indirectly, could increase the risk of death from CVDs." (PMID 36050672, 2022). "Mutations in MRAP2 and MC4R cause obesity in both humans and mice." (PMID 35588128, 2022). "The compound heterozygous carriers of pathogenic genetic variants in the autosomal recessive genes LEP, LEPR, POMC and PCSK1 are rare, obesity-associated variants in the autosomal dominant gene MC4R are the most common, with 0.8% of participants in our study carrying a variant in MC4R." (PMID 35574020, 2022). "Targeted deletion of miR-7 in Single-minded homolog 1 (Sim1) neurons, a critical component of the hypothalamic melanocortin pathway, causes hyperphagia, obesity and increased linear growth, mirroring Sim1 and Melanocortin-4 receptor (MC4R) haplo-insufficiency in mice and humans." (PMID 36175420, 2022). "Therefore, daisaikoto was thought to exert anti-obesity effects in MC4R gene-deficient mice by recovering of the homeostatic heat production and basal metabolism inhibited by MC4R deficiency." (PMID 35710868, 2022). "MC4R dysfunction causes obesity in both humans and knockout mice." (PMID 35955479, 2022).
Obesity (continued). "MC3R and MC4R are GPCRs mainly expressed in the central nervous system and involved in energy homeostasis, regulating food intake and energy expenditure; mutations in their corresponding genes lead to early-onset severe obesity." (PMID 36093106, 2022). "Mutations in the MC4R are the most frequent monogenic cause for obesity." (PMID 36009013, 2022). "It is well recognized that brain insulin has a specific role in feeding behavior and satiety and genetic variations in an obesity risk MC4R rs17782313 affect cerebrocortical insulin signaling, resulting in an impaired insulin response in the human brain, indicating a possible interaction." (PMID 35538513, 2022). "Therefore, this study aimed to analyze associations between FTO (rs9939609), FABP2 (rs1799883), and LEP (rs2167270), LEPR (rs1137101), and MC4R (rs17782313) polymorphisms and obesity-related parameters." (PMID 35627568, 2022). "Furthermore, the risk allele C for MC4R rs17782313 was linked to cardiovascular risk factors such as insulin resistance and hypertension, as well as a higher susceptibility to obesity and inflammation." (PMID 36324080, 2022). "A few specific mutations in the MC4R gene cause monogenic obesity, while other variants located within this gene or in its vicinity have been associated with eating behavior patterns, higher risk of obesity, cardiovascular risk factors and metabolic phenotypes." (PMID 35571924, 2022). "Thus, this study aimed to examine the associations between FTO (rs9939609), FABP2 (rs1799883), LEP (rs2167270), LEPR (rs1137101), and MC4R (rs17782313) polymorphisms and obesity-related traits." (PMID 35627568, 2022). "Previous research has found the association of MC4R mutations with obesity: a wide variety of heterozygous loss‐of‐function mutations cause a morbid early‐onset obesity syndrome or hyperphagia whereas gain‐of‐function mutations that increase receptor activity are associated with leanness." (PMID 35818295, 2022). "Similarly, MC4R (rs17782313) is associated with high dietary intake and different obesity-related phenotypic traits, such as insulin resistance, type 2 diabetes, and hypertriglyceridemia." (PMID 34683180, 2021). "Mutations in the leptin-melanocortin signaling pathway, most of which occur in the melanocortin 4 receptor (MC4R), may account for much of the heritability of obesity: an estimated 1 in 200 obese people worldwide have disease-causing mutations in MC4R." (PMID 34777390, 2021). "In one study on binge-eating in severe obesity associated with MC4R and LEPR variants, it was observed that prevalence of binge-eating in LEPR heterozygous variant carriers, including p.R612H variant, was higher than in controls, but no individual cases were reported." (PMID 34448070, 2021). "Physical activity attenuates the effect of the MC4R polymorphism on obesity in men." (PMID 34205732, 2021). "MC4R variants represent the most frequent cause of monogenic obesity." (PMID 32952152, 2021). "Loss-of-function MC4R variants are among the most common genetic causes of early-onset obesity in humans, while gain-of-function MC4R variants are associated with protection from obesity and its complications." (PMID 33937937, 2021). "We analysed whether dietary factors may attenuate the associations between MC4R genotypes and obesity and metabolic parameters." (PMID 34769477, 2021). "The risk of obesity was higher among sedentary Spain adults with MC4R risky C allele." (PMID 34205732, 2021). "Additionally, heterozygous mutations in MC4R that impair cAMP production represent the commonest monogenic form of obesity." (PMID 33761344, 2021). "Here, we report the development of 2 mechanistically distinct MC4R-linked obesity models." (PMID 33434184, 2021). "However, in the case of mutations in the MC4R gene, severe early-onset obesity has been reported in multiple affected members of several families who only carried heterozygote LoF mutations." (PMID 34045736, 2021).
Obesity (continued). "Mice carrying the WT allele of the human MC4R (WT-hMC4R) in place of the mouse MC4R (mMC4R) gene developed a “hypomorphic” phenotype leading to obesity because of a lower sensitivity of the human receptor to α–melanocyte-stimulating hormone (α-MSH) as compared with the mouse receptor." (PMID 33434184, 2021). "Quantitative variation in MC4R signaling plays a pivotal role in energy homeostasis, as the loss of one MC4R allele is sufficient to cause severe obesity in rodents and humans." (PMID 33761344, 2021). "MC4R screening in a large eMERGE cohort confirmed many previous findings, extend the MC4R pleotropic effects, and discovered additional MC4R rare alleles that probably contribute to obesity." (PMID 32952152, 2021). "In humans, Mc4r loss-of-function mutations account for about 5% of all early-onset obesity cases." (PMID 34512392, 2021). "MC4R receptor signalling mediates the effect of leptin on food intake and energy homeostasis and has been implicated in the regulation of feeding behaviour and body weight in humans and mice, with agonists of MC4R reducing food intake and targeted mutation of MC4R causing obesity." (PMID 34461824, 2021). "Mutations in the melanocortin 4 receptor (MC4R) are the most common cause of monogenic obesity." (PMID 34156126, 2021). "This prompted us to investigate whether the MC4R p.Ile269Asn mutation increases T2D risk via obesity-dependent or independent mechanisms in the Mexican population." (PMID 33542413, 2021). "The present study shows that MC4R mutations are reported to develop obesity ranging from 0.5–5.8%." (PMID 34836030, 2021). "In cats, environmental factors such as obesity and physical inactivity have been linked with DM, although to date, the only genetic association that has been demonstrated is with a polymorphism in the feline MC4R gene." (PMID 34874954, 2021). "In addition, previous research has established that MC4R deletion or mutation results in obesity, hyperphagia, and insulin resistance." (PMID 34696776, 2021). "MC4R has a key role coordinating energy balance, glucose homeostasis, and sympathetic nerve activity, and impaired MC4R function has been related with overfeeding and the development obesity and associated metabolic alterations in animal models and humans." (PMID 34579137, 2021). "Finally, a Spanish study described that among children with obesity, carriers of MC4R mutations (n = 8) achieved similar or greater reduction in BMI-SDS loss compared to noncarriers (n = 103) after a short 8-week lifestyle intervention." (PMID 32921795, 2021). "MC4R plays a pivotal role in the regulation of body weight, as demonstrated in animal models and in humans, in which variants that cause a LoF by reducing cAMP production are associated with obesity." (PMID 33761344, 2021). "In the hypothalamus, ectopic expression of agouti causes obesity due to its antagonism of MC4R." (PMID 33716796, 2021). "The interactions between MC4R genetic variants and dietary factors may play a significant role in the development of obesity and type 2 diabetes phenotypes, which highlight the need for additional research on this topic." (PMID 34769477, 2021). "Therefore, the current study has been undertaken to compute the GRS based on five obesity-linked key loci including MC4R rs17782313, BDNF rs6265, FTO rs1421085, TMEM18 rs7561317, and NEGR1 rs2815752 in this at-risk and under-represented population." (PMID 33859285, 2021). "However, a first causal treatment option with the MC4R agonist setmelanotide is recently available in the context of clinical studies for certain patients with monogenic obesity." (PMID 33140236, 2020). "Furthermore, a recent study based on data from 0.5 million individuals in the UK Biobank demonstrated that gain-of-function MC4R variants were associated with protection against obesity." (PMID 32733386, 2020).
Obesity (continued). "Furthermore, only genotype-array data were available for all participants, which captured roughly half of all MC4R mutations previously reported to cause severe early onset obesity." (PMID 32692746, 2020). "Multiple variants within and near the MC4R gene have been shown to be associated with metabolic diseases; indeed, these have been reported to be the most frequent genetic cause of obesity in humans, with more than 150 variants reported in patients with various ethnic origins." (PMID 32733386, 2020). "Complementing these pharmacological studies, loss-of-function mutations of Pomc or Mc4r, or over-expression of Agrp, promote hyperphagia, obesity, and insulin resistance in multiple species, including zebrafish, mice, dogs, and man, illustrating the strong translational nature of this system." (PMID 32166324, 2020). "MC4R rs13447324 is a nonsense variant associated with obesity." (PMID 31797629, 2020). "Mutations in the MC4R gene arethe most common cause of monogenic obesity in humans." (PMID 33659800, 2020). "Mutations in this G protein coupled receptor (GPCR) are the most common cause for monogenetic obesity, which appears to be mediated by changes in the anorectic action of MC4R via GS-dependent cyclic adenosine-monophosphate (cAMP) signaling as well as other signaling pathways." (PMID 32059383, 2020). "Mutations in POMC and MC4R genes lead to severe obesity due to hyperphagia." (PMID 32982666, 2020). "In human pathology, MC4R deficiency is responsible for 6% of monogenic obesity." (PMID 33374435, 2020). "In contrast to previous, mainly small-scale, often case-focused studies that reported mutations in MC4R claimed to cause severe early onset obesity, we leveraged data from over 450,000 individuals and conducted one of the largest studies to validate MC4R mutations to date." (PMID 32692746, 2020). "Of the 59 MC4R mutations available in the UK Biobank, only 11 had an impact on obesity risk." (PMID 32692746, 2020). "Variants in MC4R have been reported in 3%−5% of early onset or severe adult obesity cases." (PMID 32733386, 2020). "The standard form of monogenic obesity reported so far is the MC4R deficiency." (PMID 33113859, 2020). "Notably, those data show that the genetic background against which the MC4R mutation occurs has a large influence on the penetrance of the obesity phenotype." (PMID 33233816, 2020). "Current research has identified an association between the MC4R mutations and obesity." (PMID 32770936, 2020). "Moreover, human obesity-associated MC4R mutations disrupt the ciliary localization of MC4R, implying the importance of ciliary localization of MC4R in the maintenance of normal energy balance." (PMID 33188191, 2020). "Furthermore, the impact of the obesity-increasing MC4R mutations is substantially attenuated in individuals with a low polygenic susceptibility compared with those with a high polygenic susceptibility." (PMID 32692746, 2020). "Taken together, our findings suggest that, in addition to existing case-focused studies and in vitro functional analyses, large-scale population data are required to more accurately assess the impact of MC4R mutations (and potentially others) on severe early onset obesity." (PMID 32692746, 2020). "Studies reporting on MC4R mutations that cause severe and early onset obesity have typically been small and case-focused studies and may therefore have overestimated their impact." (PMID 32692746, 2020). "The obesity phenotype of MC4R heterozygous mutations carriers is highly variable." (PMID 33261141, 2020). "Association signals were identified between MC4R exonic variants and different levels of obesity." (PMID 31947684, 2020). "Conversely, a non-coding region located at 3′ of MC4R might harbor variants related to obesity risk, according to a GWAS analysis of the European population." (PMID 31947684, 2020).